DRG1 (developmentally regulated GTP binding protein 1)
Description:
Catalyzes the conversion of GTP to GDP through hydrolysis of the gamma-phosphate bond in GTP. Appears to have an intrinsic GTPase activity that is stimulated by ZC3H15/DFRP1 binding likely by increasing the affinity for the potassium ions. When hydroxylated at C-3 of 'Lys-22' by JMJD7, may bind to RNA and play a role in translation. Binds to microtubules and promotes microtubule polymerization and stability that are required for mitotic spindle assembly during prophase to anaphase transition. GTPase activity is not necessary for these microtubule-related functions.
Synonyms: NEDD3; TANALS
Tractability: PROTAC: UniProt records ubiquitination sites on it; ubiquitination databases record sites on it; its protein half-life has been measured.
Target class: Enzyme; Hydrolase
Gene: Protein-coding gene on chromosome 22 (31,399,560 to 31,528,740, forward strand). Ensembl gene ENSG00000185721.
Subcellular location: Nucleus; Cytoplasm
Subcellular location (Human Protein Atlas): Nuclear bodies; Nucleoplasm; Cytosol
Pathways (Reactome):
Metabolism of proteins: Protein hydroxylation
Gene Ontology:
Molecular function: GTPase activity; identical protein binding; microtubule binding; potassium ion binding; protein binding; GTP binding
Biological process: positive regulation of microtubule polymerization; regulation of mitotic spindle assembly; cytoplasmic translation
Cellular component: cytoplasm; cytosol; membrane; nuclear body; nucleoplasm; nucleus
Genetic constraint (gnomAD): Loss-of-function variants: 19 observed, 39.93 expected, observed/expected ratio (o/e) 0.48, 90% interval 0.33 to 0.7. The upper end of that interval is the gene's LOEUF score, 0.7, which puts it in group 2 of 6, group 1 being the genes least tolerant of losing a copy. Missense variants: 299 observed, 465.81 expected, observed/expected ratio (o/e) 0.64, 90% interval 0.58 to 0.71. Synonymous variants: 167 observed, 166.05 expected, observed/expected ratio (o/e) 1.01, 90% interval 0.89 to 1.14.
Homologues: Orthologues: chimpanzee DRG1 (100% identical), dog DRG1 (100% identical), guinea pig DRG1 (100% identical), macaque DRG1 (100% identical), rabbit DRG1 (100% identical), mouse Drg1 (99% identical), pig DRG1 (99% identical), rat Drg1 (99% identical), tropical clawed frog drg1 (95% identical), zebrafish drg1 (92% identical), Drosophila melanogaster 128up (81% identical), Caenorhabditis elegans T28D6.6 (81% identical). Paralogues in human: DRG2 (57% identical), GTPBP10 (21% identical), MTG2 (21% identical), GTPBP4 (20% identical).
Diseases named in the same sentence as DRG1 in open-access papers:
DRG1 is named in the same sentence as 25 diseases in open-access papers, as found by Europe PMC text mining. Sharing a sentence is not in itself a finding about the gene and the disease. The quoted sentences say what the papers report.
prostate carcinoma (7 papers, 2012 to 2020). A carcinoma that arises from epithelial cells of the prostate gland. "DRG-1 overexpression has also been associated with favorable clinical outcome in patients with breast cancer, prostate cancer, esophageal squamous cell carcinoma, pancreatic cancer, and neuroblastoma." (PMID 25993655, 2015). "Specifically, microRNAs such are miR-346 and miR-361-3p were suggested to modulate the expression of PSA, TMPRSS2 and DRG1 in prostate cancer." (PMID 33245732, 2020). "In contrast, DRG-1 has been shown to suppress the metastasis of colon and prostate cancers in the in vivo mouse models." (PMID 25993655, 2015). "Low DRG1 expression correlates with higher grade of prostate cancer, development of metastases, and with poor patient survival." (PMID 24213460, 2012). "Drg-1 is located in the cytoplasm of human EJ bladder carcinoma cells, human hepatocellular carcinoma cells, and human prostate cancer cells." (PMID 23013480, 2012). "An inverse correlation has been reported between DRG1 expression and the metastatic potential of prostate cancer cells." (PMID 24213460, 2012). "The increase in invasiveness in the MCF7 cell line is consistent with findings that suggest that over-expression of DRG1 reduces the invasiveness of breast, colon and prostate cancer cells." (PMID 24213460, 2012). "This follows the observation that individuals with higher DRG1 tumour levels have greater survival rates, in breast and prostate cancer patients." (PMID 24213460, 2012). "Also in favor of oncogenicity, the tumor suppressor gene Drg-1 mediates its anti-metastatic properties through ATF3 downregulation in prostate cancer." (PMID 24494067, 2013). "Interestingly, a study examining DRG1 expression in African-American prostate cancer patients has found that they have significantly reduced expression of this protein when compared with Caucasian prostate cancer patients." (PMID 24213460, 2012). "Some studies have indicated that DRG1 expression is up regulated in prostate cancer compared with corresponding normal tissue but that this could be due to its response to hormones such as androgens." (PMID 24213460, 2012).
breast carcinoma (5 papers, 2012 to 2022). "In breast cancer, low DRG1 expression is associated with more advanced cancer stage and worse survival." (PMID 24213460, 2012). "However, lower DRG1 expression was found to be associated with advanced stages of cancer and very low survival rates in breast cancer patients." (PMID 32266933, 2020). "Sucharita Bandyopadhyay observed that DRG-1 expression was reduced in breast cancer cells, especially in cells from patients with bone metastases." (PMID 36497209, 2022). "A few other studies have also reported DRG1 to be a tumour suppressor with role in suppression of metastasis in prostate and breast cancer; however, an exact role and relevance of this protein in meningiomas is not known." (PMID 28938569, 2017). "The knockdown of DRG1 expression had little impact on the growth of the tested breast cancer cells over the 3 and 5 day incubation periods." (PMID 24213460, 2012). "The enhanced motility and decreased adhesiveness of DRG1 knockdown MCF7 breast cancer cells demonstrated by this study further suggest a metastasis suppressive role for this gene." (PMID 24213460, 2012). "In conclusion, the in vitro andclinical data presented here indicate an involvement of the DRG1 gene in breast cancer progression and demonstrate a potential role of this gene in suppressing tumour metastasis." (PMID 24213460, 2012). "The current study aimed to verify the expression profile of DRG1 in a cohort of breast cancer patients and to compare it with the clinical data." (PMID 24213460, 2012). "Transfection of MCF7 and MDA-MB-231 breast cancer cells with the DRG1 ribozyme transgene successfully knocked down the expression of this molecule." (PMID 24213460, 2012). "Low levels of DRG1 were found in patients who developed metastasis (p = 0.036) and who died of breast cancer (p = 0.0048) compared to disease free patients." (PMID 24213460, 2012). "The aim of the current study was to investigate the expression profile of DRG1 in a cohort of breast cancer patients and compare this expression profile with clinical outcomes of patients in the cohort." (PMID 24213460, 2012). "The electric cell substrate impedance sensing (ECIS) system was used to examine the effect of DRG1 knockdown on breast cancer cell migration." (PMID 24213460, 2012). "Patients who were disease-free were found to have significantly higher levels of DRG1 transcripts than those who developed metastasis and those who died of breast cancer (p = 0.036 and 0.0048 respectively)." (PMID 24213460, 2012). "Furthermore, DRG-1 expression was reduced in clinical samples from breast cancer patients with metastasis to lymph nodes and bones." (PMID 25993655, 2015). "Interestingly, knockdown of DRG1 seemed to impact on cell-matrix adhesion differently in the two tested breast cancer cell lines." (PMID 24213460, 2012). "Additionally, DRG1 expression is targeted in vitro using ribozyme transgene technology to explore the function of DRG1 in two human breast cancer cell lines." (PMID 24213460, 2012). "Additionally, this study aimed to explore the role of DRG1 on cellular functions such as growth, adhesion, invasion and cellular migration in breast cancer cell lines, using a series of in vitro cell models." (PMID 24213460, 2012). "DRG1 expression was observed in both the MCF7 and MDA-MB-231 human breast cancer cell lines available." (PMID 24213460, 2012). "Thus, DRG1 appears to be linked to development of metastasis and death in patients who died as a result of breast cancer and may be useful as a prognostic factor as its knockdown appears to be linked with increased invasion and motility and decreased adhesion in MCF7 breast cancer cells." (PMID 24213460, 2012). "The results of our current study also suggest a potential role of DRG1 in cell adhesion, invasion and motility as knockdown of this molecule in MCF7 breast cancer cells decreased the adhesive ability of this cell line while increasing invasiveness and migratory capacity." (PMID 24213460, 2012).
osteosarcoma (5 papers, 2012 to 2024). A usually aggressive malignant bone-forming mesenchymal neoplasm, predominantly affecting adolescents and young adults. "DRG1 has been implicated in various tumors, including melanoma, osteosarcoma and lung cancer, as well as in various tumor cell lines." (PMID 35790840, 2022). "A study with human U2OS osteosarcoma cells expressing Drg-1 small interfering RNA showed that Drg-1 is associated with the production of osteocalcin." (PMID 23013480, 2012). "Additionally, overexpressed sponge and human DRG1 increases cell migration, which is consistent with the findings that DRG1 deficiency lowers cell migration and colony-formation in osteosarcoma cells." (PMID 35790840, 2022). "A recent report has shown evidence that DRG1 is overexpressed in osteosarcoma, where its expression is correlated with tumor size and clinical progression." (PMID 34664086, 2021). "In osteosarcoma, knockdown of METTL3 decreases mRNA and protein levels of DRG1, which further leads to G2/M phase cell cycle arrest and inhibits osteosarcoma cell proliferation." (PMID 39289775, 2024).
colon cancer (3 papers, 2010 to 2012). "As one example, Drg-1, identified by differential display, is downregulated in its expression in metastatic colon cancer and its forced overexpression reduces in vitro invasion of colon cancer, these findings leading the authors to propose Drg-1 as a metastatic suppressor." (PMID 20087350, 2010). "In colon cancer cells, activation of PPARγ by troglitazone treatment inhibits growth and metastasis through differentiation-promoting effects, such as the marked increase in p21 Waf-1, developmentally regulated GTP-binding protein 1 (DRG-1), and E-cadherin in human colon cancer cells." (PMID 23024650, 2012).
colorectal cancer (3 papers, 2012 to 2020). A primary or metastatic malignant neoplasm that affects the colon or rectum. "For example, high Drg1 expression is more likely associated with a less aggressive and indolent colorectal cancer." (PMID 32266933, 2020). "Low DRG1 expression was also associated with a more aggressive kind of colorectal cancer, while high DRG1 expression enhanced irinotecan resistance in colorectal cancer." (PMID 32266933, 2020). "In colorectal cancer, it has been suggested that DRG1 expression may be associated with a less aggressive, indolent colorectal cancer." (PMID 24213460, 2012). "This is also supported by a study examining DRG1 expression in colorectal cancer and comparing it with patient outcomes." (PMID 24213460, 2012).
lung adenocarcinoma (3 papers, 2016 to 2022). A carcinoma that arises from the lung and is characterized by the presence of malignant glandular epithelial cells. "This was the first time to show that DRG1 was an important protein involved in spindle checkpoint signaling, and elevated levels of DRG1 caused lung adenocarcinoma and taxol resistance." (PMID 27626498, 2016). "In this study, we trained and validated 16 DDR genes with prognostic values and classification effects in early-stage lung adenocarcinoma and classified patients into two subtypes, DRG1 and DRG2." (PMID 35813819, 2022). "In lung adenocarcinoma, overexpressed DRG1 increased cell proliferation by regulating cell cycle proteins and enhanced resistance against paclitaxel (Taxol)." (PMID 32266933, 2020). "Obviously, DRG1 participated in the regulation of mitosis, and this was one of the mechanisms that overexpression of DRG1 triggered lung adenocarcinoma." (PMID 27626498, 2016). "DRG1 mRNA expression exhibited significant upregulation in randomly selected 5 out of 6 lung adenocarcinoma tissues." (PMID 27626498, 2016). "Here, we demonstrate that DRG1 is elevated in lung adenocarcinomas while weakly expressed in adjacent lung tissues." (PMID 27626498, 2016). "Then, we confirm that DRG1 mRNA was significantly up-regulated in lung adenocarcinoma compared with adjacent tissues according to the microarray data in oncomine, including human genome U133A array data, U133 Plus 2.0 array data and U95A-Av2 array data." (PMID 27626498, 2016). "In the present study, we identified DRG1 as a new oncogene in lung adenocarcinoma." (PMID 27626498, 2016). "In conclusion, we uncovered the upregulated expression of DRG1 in lung adenocarcinoma." (PMID 27626498, 2016). "Interestingly, ectopic of DRG1 reduces taxol induced apoptosis of lung adenocarcinoma cells." (PMID 27626498, 2016). "We then investigated whether there was evidence linking DRG1 protein to lung adenocarcinoma." (PMID 27626498, 2016). "Notably, expression levels of DRG1 were substantially increased in lung adenocarcinoma." (PMID 27626498, 2016).
lung carcinoma (3 papers, 2016 to 2022). "However, little is known about the molecular mechanism underling growth regulation and it is unknown whether DRG1 plays a role in lung cancer, which is the leading cause of death from cancer." (PMID 27626498, 2016).
melanoma (3 papers, 2015 to 2022). A malignant, usually aggressive tumor composed of atypical, neoplastic melanocytes. "Herein, we describe the identification and characterization of developmentally regulated GTP-binding protein 1 (DRG-1) as a melanoma-associated antigen recognized by HLA-DR11-restricted CD4+ Th1 cells." (PMID 25993655, 2015). "To this end, we describe the identification of developmentally regulated GTP-binding protein 1 (DRG-1) as a melanoma-associated antigen recognized by HLA-DR11-restricted CD4+ Th1 cells." (PMID 25993655, 2015). "Our study identified DRG-1 as a melanoma-associated antigen capable of activating CD4+ Th1 cells." (PMID 25993655, 2015). "In conclusion, we identified DRG-1 as a melanoma-associated antigen recognized by CD4+ Th1 cells." (PMID 25993655, 2015). "Interestingly, the authors of this study also identified DRG1 as a melanoma-associated antigen that is recognized by CD4 + T cells, raising the possibility that it could be a novel target for cancer immunotherapy." (PMID 34664086, 2021). "DRG1 is also overexpressed in melanoma, where its knock-down reduces cell proliferation and soft agar colony formation." (PMID 35790840, 2022). "DRG1 is also overexpressed in melanoma, where knocking down its expression reduces cell proliferation and soft agar colony formation." (PMID 34664086, 2021). "Although most tumor-associated antigens are not required for tumor growth, gain-of-function and shRNA-mediated knockdown experiments demonstrated the critical role of DRG-1 in the growth and proliferation of melanoma cells." (PMID 25993655, 2015). "Taken together, these data suggested that DRG-1 plays an important role in melanoma development and progression." (PMID 25993655, 2015). "The expression pattern of DRG-1 was determined in melanoma cell lines and normal tissues using RT-PCR." (PMID 25993655, 2015). "The elevated expression of DRG-1 in melanoma cells suggested the potential involvement of DRG-1 in the oncogenic process in melanoma." (PMID 25993655, 2015). "DRG-1 knockdown by lentiviral-based shRNA suppressed melanoma cell proliferation and soft agar colony formation." (PMID 25993655, 2015). "DRG-1 knockdown significantly inhibited the transformation ability of melanoma cells as evidenced by the lower colony number compared with control cells (P < 0.05)." (PMID 25993655, 2015). "Gain-of-function and shRNA knockdown experiments revealed that DRG-1 promotes the proliferation and transformation of melanoma cells." (PMID 25993655, 2015). "Therefore, our findings strongly suggest the involvement of DRG-1 in melanoma development and progression." (PMID 25993655, 2015). "Taken together, these data suggest that DRG-1 plays an important role in melanoma cell growth and transformation, indicating that DRG1 may represent a novel target for CD4+ T cell-mediated immunotherapy in melanoma." (PMID 25993655, 2015). "DRG-1 may represent a potentially useful target for the development of immunotherapy regimens for melanoma patients." (PMID 25993655, 2015). "We found that DRG-1 promoted the proliferation and anchorage-independent growth of melanoma cells." (PMID 25993655, 2015). "Together, our findings indicate that DRG-1 may represent a novel target for melanoma immunotherapy." (PMID 25993655, 2015). "Thus, DRG-1-specific Th1 cells may play a role in controlling tumor growth in melanoma patients." (PMID 25993655, 2015). "Reverse transcription-polymerase chain reaction revealed that DRG-1 was highly expressed in melanoma cell lines but not in normal tissues." (PMID 25993655, 2015). "DRG-1 was highly expressed in most melanoma cell lines, whereas DRG-1 expression was low or absent in normal tissues, with the exception of normal testis." (PMID 25993655, 2015). "DRG-1 was highly expressed in most melanoma cell lines, whereas its expression was low or absent in normal tissues." (PMID 25993655, 2015).
melanoma (continued). "In the present study, DRG-1 was highly expressed in melanoma cell lines, whereas DRG-1 expression was low or absent in normal tissues with the exception of normal testis." (PMID 25993655, 2015).
hepatocellular carcinoma (2 papers, 2012 to 2015). A malignant tumor that arises from hepatocytes. "DRG-1 has also been shown to be a predictor of poor prognosis in hepatocellular carcinoma, NSCLC, and cervical adenocarcinoma." (PMID 25993655, 2015). "Moreover, hepatocellular carcinomas that are moderately and poorly differentiated express a higher level of Drg-1 than those that are well differentiated." (PMID 23013480, 2012). "Human hepatocellular carcinomas express a higher level of Drg-1 than non-tumor liver or cirrhotic and benign liver lesions." (PMID 23013480, 2012).
pancreatic cancer (2 papers, 2012 to 2015). "Kaplan-Meier analysis of pancreatic cancer patients showed a statistically significant correlation of DRG1 expression with survival." (PMID 24213460, 2012). "Furthermore, DRG-1 expression is correlated with microvessel density, a measure of tumor angiogenesis, in patients with cervical adenocarcinoma and pancreatic cancer." (PMID 25993655, 2015).
brain cancer (1 paper, 2015). A primary or metastatic malignant neoplasm affecting the brain. "DRG-1 expression is increased in many types of human tumors including colon, breast, prostate, kidney, liver, and brain cancers." (PMID 25993655, 2015).
breast tumour (1 paper, 2012). "Our data suggests that DRG1, reported to be a potential suppressor of metastasis, is aberrantly expressed in breast tumour tissues." (PMID 24213460, 2012).
necrotizing enterocolitis (1 paper, 2024). Necrotizing enterocolitis (NEC) is a devastating disease that affects mostly the intestine of premature infants. "Both DRG1, which has been seen to have a protective effect on epithelial junction proteins under the conditions of necrotizing enterocolitis, and MUC2 were uniquely upregulated by HFD+OC." (PMID 39588046, 2024).
prostate tumours (1 paper, 2012). "This is also consistent with a previous report in which DRG1 mRNA was shown to be reduced in a small set of breast and prostate tumours by in situ hybridization." (PMID 24213460, 2012).